RNU6-711P (RNA, U6 small nuclear 711, pseudogene)
Gene: Small nuclear RNA gene on chromosome 17 (29,424,762 to 29,424,867, reverse strand). Ensembl gene ENSG00000253064.
Homologues: Orthologues: chimpanzee U6 (98% identical), macaque U6 (92% identical), dog U6 (82% identical). Paralogues in human: RNU6-1331P (88% identical), RNU6-189P (87% identical), RNU6-727P (87% identical), RNU6-1094P (86% identical), RNU6-1287P (86% identical), RNU6-238P (86% identical), RNU6-66P (86% identical), RNU6-1243P (85% identical), RNU6-242P (85% identical), RNU6-315P (85% identical), RNU6-797P (85% identical), RNU6-1091P (84% identical), and 1286 more.